AMPH (amphiphysin)
Description:
May participate in mechanisms of regulated exocytosis in synapses and certain endocrine cell types. May control the properties of the membrane associated cytoskeleton.
Synonyms: AMPH1
Tractability: Antibody: UniProt places it where antibodies can reach, with medium confidence; its Gene Ontology location is reachable by antibodies, with medium confidence. PROTAC: ubiquitination databases record sites on it; its protein half-life has been measured.
Gene: Protein-coding gene on chromosome 7 (38,383,700 to 38,631,507, reverse strand). Ensembl gene ENSG00000078053.
Subcellular location: Cytoplasmic vesicle, secretory vesicle, synaptic vesicle membrane; Cytoplasm, cytoskeleton
Subcellular location (Human Protein Atlas): Cytosol; Plasma membrane
Pathways (Reactome):
Vesicle-mediated transport: Clathrin-mediated endocytosis
Gene Ontology:
Molecular function: phospholipid binding; protein binding
Biological process: chemical synaptic transmission; endocytosis; synaptic vesicle endocytosis
Cellular component: cytosol; leading edge membrane; actin cytoskeleton; plasma membrane; synaptic vesicle; cytoplasm; cytoskeleton; synaptic vesicle membrane
Genetic constraint (gnomAD): Loss-of-function variants: 42 observed, 77.91 expected, observed/expected ratio (o/e) 0.54, 90% interval 0.42 to 0.7. The upper end of that interval is the gene's LOEUF score, 0.7, which puts it in group 2 of 6, group 1 being the genes least tolerant of losing a copy. Missense variants: 715 observed, 803.41 expected, observed/expected ratio (o/e) 0.89, 90% interval 0.84 to 0.95. Synonymous variants: 296 observed, 298.18 expected, observed/expected ratio (o/e) 0.99, 90% interval 0.9 to 1.09.
Homologues: Orthologues: macaque AMPH (98% identical), chimpanzee AMPH (96% identical), pig AMPH (88% identical), rabbit AMPH (88% identical), dog AMPH (88% identical), guinea pig AMPH (87% identical), rat Amph (83% identical), mouse Amph (81% identical), tropical clawed frog amph (67% identical), zebrafish amph (50% identical), Drosophila melanogaster Amph (24% identical). Paralogues in human: BIN1 (42% identical), BIN2 (25% identical), BIN3 (9% identical).
Diseases named in the same sentence as AMPH in open-access papers:
AMPH is named in the same sentence as 100 diseases in open-access papers, as found by Europe PMC text mining. Sharing a sentence is not in itself a finding about the gene and the disease. The quoted sentences say what the papers report.
breast carcinoma (22 papers, 2013 to 2026). "Paraneoplastic causes typically involve breast cancer or small cell lung cancer and are anti-amphiphysin positive." (PMID 40666555, 2025). "The paraneoplastic variant of SPS is more common in patients with breast cancer with anti-amphiphysin antibodies, followed by colon carcinoma, lung carcinomas, thymoma, and Hodgkin's lymphoma." (PMID 36968894, 2023). "Breast cancer has been linked to decreased AMPH-1 expression and activation of EMT and ERK pathways." (PMID 37554401, 2023). "Malignancies such as small cell lung cancer and breast cancer triggered amphiphysin-Abs associated paraneoplastic neurological syndromes (PNSs) have been reported." (PMID 36685551, 2022). "Amphiphysin antibody is an onconeural antibody linked to the diagnosis of breast cancer and small-cell lung cancer." (PMID 33766120, 2021). "There has been no published report on the association between the presence of amphiphysin antibodies in breast cancer and bilateral facial nerve palsy." (PMID 33766120, 2021). "An amphiphysin antibody is an onconeural antibody that has been identified and linked to the diagnosis of breast cancer and small-cell lung cancer (SCLC)." (PMID 33766120, 2021). "Studies have shown that the paraneoplastic variant of SPS is more common in patients with breast cancer who harbour amphiphysin antibodies, followed by colon cancer, lung cancer, Hodgkin's disease, and malignant thymoma." (PMID 26848416, 2015). "Finally, Stiff-Person Syndrome (SPS) is typically non-paraneoplastic (anti-GAD65), but paraneoplastic variants occur, notably in women with breast cancer and anti-amphiphysin antibodies." (PMID 41562781, 2026). "“Intermediate-” and “low-risk” syndromes, such as encephalitis and SPSD, can also be paraneoplastic, the former when associated with anti-Ri/ANNA-2 (breast cancer) or anti-Ma2 (testicular cancer) antibodies, and the latter when associated with anti-amphiphysin (SCLC) antibodies." (PMID 37239077, 2023). "Paraneoplastic SPS is mostly associated with amphiphysin antibodies and breast cancer." (PMID 34006622, 2021). "Similarly, two cases of encephalomyelitis and SPS in association with breast carcinoma have been reported and were associated with anti-amphiphysin antibodies." (PMID 27800287, 2015). "In addition to SPS, AMPH autoimmunity has been associated with various neurological manifestations, including encephalitis and peripheral neuropathy, and various types of malignancies, including breast cancer, small-cell lung carcinoma, and gastric cancer." (PMID 37416304, 2023). "Breast cancer is strongly linked to anti-Yo (PCA-1), anti-Ri (ANNA-2), and anti-amphiphysin antibodies." (PMID 41562781, 2026). "The individuals with anti-amphiphysin identified mostly presented with classic SPS phenotype, and all but one was paraneoplastic associated with breast cancer." (PMID 38078976, 2024). "Amphiphysin antibodies are typically observed in patients affected by SCLC and breast cancer; however, these antibodies are rarely associated with limbic encephalitis." (PMID 38391750, 2024). "Around 90% of SPS patients with amphiphysin antibody have been found to have breast cancer during their illness." (PMID 33766120, 2021). "A small number of case reports have described the link between amphiphysin antibodies with these classical neurological syndromes in patients with breast cancer and SCLC." (PMID 33766120, 2021). "In the study, all the anti-amphiphysin SPS patients were female and 10 of them had underlying breast cancer." (PMID 27800287, 2015). "There is one reported case of breast cancer related SPS with a positive anti-amphiphysin titer and complicated by rhabdomyolysis." (PMID 27800287, 2015). "The incidence of tumor of anti-Amphiphysin antibody is 46 ~ 79%, which may be related to Sheehan syndrome, breast cancer, small-cell lung cancer, and angiosarcoma." (PMID 33835270, 2021).
breast carcinoma (continued). "In addition, only 14 cases reported pathological findings coming from concomitant neoplasms (small cell lung cancer, breast cancer and non-small cell lung cancer) in which amphiphysin-IgG was present in patients’ tumor tissues, which correlated with the patients’ antibody specificity." (PMID 36685551, 2022). "Other SPS cases in the literature include a breast cancer patient found to have both anti-GAD and anti-amphiphysin antibodies." (PMID 27800287, 2015). "In paraneoplastic limbic encephalitis, the most common tumors and corresponding antibodies are SCLC (anti-Hu, anti-CRMP5, and anti-amphiphysin), testicular cancer (anti-Ma2), thymoma (anti-CRMP5), and breast cancer (anti-amphiphysin)." (PMID 23983403, 2013).
stiff-person syndrome (18 papers, 2008 to 2026). Stiff-man syndrome (SMS) is a rare neurological disorder comprising fluctuating trunk and limb stiffness, painful muscle spasms, task-specific phobia, an exaggerated startle response, and ankylosing deformities such as fixed lumbar hyperlordosis. "The presence of anti-amphiphysin autoantibodies is most commonly associated with limbic encephalitis (LE) and stiff-person syndrome." (PMID 37090693, 2023). "Injection of human serum containing high titres of antibodies to amphiphysin, a protein associated with the cytoplasmic surface of synaptic vesicles, was found to cause dose-dependent stiffness, with spasms resembling human stiff-person syndrome in rats as well as anxiety behaviour." (PMID 26377319, 2015). "For these two autoantibodies associated with different neurological diseases like stiff-man syndrome evidence for a pathogenic potential was suggested by rodent animal models showing induction of anxiety by transfer of stiff-person IgG or a reduced GABAergic inhibition by amphiphysin IgG." (PMID 30543686, 2018). "A retrospective case series of 63 patients with anti-amphiphysin autoimmunity showed that neurological presentations included neuropathy (52.4%), encephalopathy (30.2%), myelopathy (27%), stiff-person syndrome (28.6%), and cerebellar ataxia (17.5%)." (PMID 39184604, 2024). "Similarly, amphiphysin autoantibodies from patient sera transferred to rats were found to be internalized by neurons, to alter the function of inhibitory synapses in vivo, and to cause dose-dependent stiffness, with spasms resembling human stiff-person syndrome, as well as anxiety behaviour." (PMID 35907972, 2022). "Subsequently, autoantibodies against synaptic proteins were described, first against amphiphysin in “three women with the stiff-man syndrome and breast cancer” and then against gephyrin in one SMS patient." (PMID 35084720, 2022). "In our study, patients with anti-AMPAR encephalitis were noted to also have stiff-person syndrome (anti-GAD) or sensory neuropathy (anti-amphiphysin)." (PMID 36211351, 2022). "Autoantibodies against proteins involved in GABAergic transmission, including anti-glutamic acid decarboxylase (GAD) 65, anti-GAD67, and anti-amphiphysin, are the putative autoantibodies for cerebellar ataxia, stiff person syndrome, and Batten’s disease." (PMID 28484451, 2017). "IIn a presentation on autoimmune-mediated synaptic transmission diseases of the CNS, Christian Geis from Jena reported on stiff person syndrome with anti-amphiphysin antibodies." (PMID 23174128, 2012). "In reports of small case series, it was demonstrated that non-stiff person syndrome with anti-amphiphysin antibody showed limbic encephalitis (50%), dysautonomia (45%), cerebellar dysfunction (30%), brainstem encephalitis (20%), and peripheral neuropathy (20%)." (PMID 39184604, 2024). "However, steroids for stiff-person syndrome and especially cyclophosphamide for neuropathy have been reported to be effective in patients with anti-amphiphysin autoimmunity." (PMID 39184604, 2024). "Moreover, further intracellular autoimmune targets have been identified such as glutamate decarboxylase 65 (GAD65) and Amphiphysin in patients with the brainstem, extrapyramidal and spinal cord dysfunction, and in stiff-person syndrome respectively." (PMID 36794262, 2023). "However, there have been passive transfer experiments with IgG fractions from patients with stiff-person syndrome and anti-amphiphysin antibodies, revealing motor hyperactivity and stiffness in mice." (PMID 32668637, 2020). "Antibodies against amphiphysin rather than GAD65 have been shown to induce stiff-person syndrome-like symptoms in rats." (PMID 28484451, 2017). "Stiff-person syndrome (SPS) is a characteristic manifestation in amphiphysin-antibody-positive cases, although it did not appear as frequently as expected in our cohort." (PMID 37090693, 2023).
encephalitis (17 papers, 2015 to 2025). An acute inflammatory process affecting the brain parenchyma. "As in other forms of AE, anti-amphiphysin encephalitis presenting with acute symptomatic seizures has a lower risk of subsequent unprovoked seizure development, which perhaps explains the disappearance of seizures in most patients." (PMID 37090693, 2023). "In addition, there was one case of a retroperitoneal tumor in anti-glutamate receptor encephalitis, one case of papillary renal cell carcinoma in anti-CV2 antibody-associated encephalitis, and one case of lung squamous cell carcinoma in anti-Hu and anti-amphiphysin antibody-associated encephalitis." (PMID 37936916, 2023). "Here, we describe the clinical features of 10 anti-amphiphysin encephalitis patients and their outcomes after immunotherapy." (PMID 37090693, 2023). "The data of encephalitis patients with anti-amphiphysin antibodies were retrospectively evaluated, including demographics, neurological and laboratory findings, imaging, treatment, and prognostic predictions." (PMID 37090693, 2023). "Amphiphysin-IgG was detected in the patient’s serum and CSF by immunoblotting and tissue-based indirect immunofluorescence assay confirming the diagnosis of definite paraneoplastic amphiphysin-IgG-positive encephalitis." (PMID 36685551, 2022). "Laboratory and neuroimaging data of anti-amphiphysin encephalitis." (PMID 37090693, 2023). "The awareness of the clinical features of amphiphysin antibody-related encephalitis provides valuable information for a better understanding of the disease and may help to facilitate its early diagnosis, treatment strategy, and prognosis prediction." (PMID 37090693, 2023). "Anti-amphiphysin encephalitis is usually treated in the same way as other AE." (PMID 37090693, 2023). "Besides, antibodies against amphiphysin was noted in another case with anti‐AMPA receptor encephalitis and was assumed to be the paraneoplastic antibodies of lung cancer." (PMID 28948076, 2017). "Anti‐amphiphysin encephalitis has been very rarely reported." (PMID 28675562, 2017). "However, an in-depth understanding of amphiphysin-IgG-associated encephalitis is lacking." (PMID 37090693, 2023). "Twenty-three patients were diagnosed as anti-LGI1 encephalitis, and four patients were diagnosed as anti-GABABR encephalitis, and the other one was diagnosed as anti-amphiphysin encephalitis." (PMID 31244751, 2019). "Immunotherapy is effective for treating encephalitis patients with anti-amphiphysin antibodies, especially those without tumors." (PMID 37090693, 2023). "The autoimmune panel for encephalitis and onco- and anti-neural antibodies (NMDA, AMPA, GABA-A, GABA-B, anti-Yo, anti-Hu, anti-Ri, anti-Ma2, anti-CV22, amphiphysin) were absent in the serum." (PMID 35453524, 2022).
small cell lung carcinoma (14 papers, 2013 to 2025). Small cell lung cancer (SCLC) is a highly aggressive malignant neoplasm, accounting for 10-15% of lung cancer cases, characterized byrapid growth, and early metastasis. "Amphiphysin antibodies are widely known to be associated with both breast and small-cell lung cancers." (PMID 37090693, 2023). "In the case of anti-AMPH antibodies, breast or small cell lung cancer is usually associated." (PMID 37416304, 2023). "Underlying malignancy was screened in 37 patients and was detected in four patients: two patients with anti-GABAb antibodies had small cell lung cancer, one patient with anti-amphiphysin antibodies had non-small-cell lung cancer, and one patient with anti-Yo antibodies had meningioma)." (PMID 26771547, 2016). "Anti-amphiphysin antibodies are uncommonly detected in paraneoplastic neurologic syndromes (PNS), especially in patients with small cell lung cancer." (PMID 37773812, 2023).
lung carcinoma (11 papers, 2015 to 2026). "Some instances of the paraneoplastic Stiff-person Syndrome (SPS) are due to AMPH autoantibodies produced in breast and lung cancer patients." (PMID 37549140, 2023). "A paraneoplastic occurrence is typically seen with amphiphysin antibodies (breast and lung cancer), and rare with GAD65 antibodies." (PMID 37760941, 2023). "Subsequently, autoimmunity against other antigens in inhibitory GABAergic pathways, like amphiphysin (indicative of paraneoplastic SPSD mainly due to breast or lung cancer;), or inhibitory glycinergic pathways (Glycine receptor (GlyR) alpha 1 subunit) were identified." (PMID 37760941, 2023). "At the same time, several genes downregulated in NPRL2−/− cells are also known to be downregulated in lung cancer (FBLN2, LBH, AMPH-1), glioblastoma (ELAVL2), and liver cancer (IGFBP4)." (PMID 41469472, 2025). "Cancer predictive antibodies included CRMP-5 (4 patients: 1 case of tonsillar squamous cell, 2 mixed histology lung carcinomas and 1 SCLC), ANNA-1 (3 patients: 2 with lung carcinoma and 1 bladder carcinoma), followed by ANNA-2 (Ri) and amphiphysin antibodies in a patient with SCLC." (PMID 35370928, 2022). "Another study showed that lung cancer cases had anti-Hu, CV2 or amphiphysin antibodies with non-classical clinical presentations should not be neglected for cancer associated PNS." (PMID 34287773, 2022). "However, no antibodies typically found in patients with lung cancer and PND, including anti-Hu, anti-CV2/CMRP5, anti-amphiphysin, anti-VGCC, anti-SOX1, anti-GABABR and anti-AMPAR, were present in our patients." (PMID 27776522, 2016).
Autoimmunity (7 papers, 2022 to 2025). The occurrence of an immune reaction against the organism's own cells or tissues. "We firstly described the clinical course and pathological findings of a patient with aGCC-associated amphiphysin-IgG autoimmunity." (PMID 36685551, 2022). "According to the clinical manifestations, tumor, positive anti-amphiphysin antibody in CSF and serum, and well response to immunotherapy, aGCC associated amphiphysin-IgG autoimmunity was considered in this patient." (PMID 36685551, 2022). "Immunopathological analysis of amphiphysin-IgG autoimmunity may help to elucidate the underlying pathophysiological mechanism of the disease, but unfortunately, published data are scarce, to date, brain and/or spinal cord immunopathological reactions have only been studied in 4 patients." (PMID 36685551, 2022). "A case of anti-amphiphysin antibody autoimmunity manifesting as the rare symptom of bulbar palsy along with cerebellar ataxia, which improved with cyclophosphamide, was presented." (PMID 39184604, 2024). "The pathogenesis of anti-amphiphysin autoimmunity involves cellular and humoral immune mechanisms, and active immunotherapy appears to be a good choice of treatment." (PMID 39184604, 2024). "A case of anti-amphiphysin antibody autoimmunity presenting with multiple symptoms, including dysphagia along with cerebellar ataxia, that responded to immunotherapy, especially cyclophosphamide, is reported." (PMID 39184604, 2024). "One possible explanation for the effectiveness of immunotherapy is that amphiphysin autoimmunity appears to act through both cellular and humoral immunity." (PMID 39184604, 2024). "Neuropathological studies of anti-amphiphysin autoimmunity showed a predominance of cytotoxic T-cells throughout the brainstem and spinal cord parenchyma." (PMID 39184604, 2024). "Regarding clinical features, while SPS and PERM are the most frequent syndromes in adult anti-GlyR and anti-amphiphysin autoimmunity, in children isolated epileptic syndromes and limbic encephalitis appear predominant, respectively." (PMID 35515348, 2022). "In addition to anti‐AMPAR antibodies, some patients also have other autoimmune antibodies, including antinuclear antibodies, anti‐amphiphysin, and anti‐CV2 antibodies." (PMID 41153078, 2025). "Moreover, while SPS and PERM are the most frequent syndromes in adult anti-GlyR and anti-amphiphysin autoimmunity, in children isolated epileptic syndromes and limbic encephalitis appear predominant, respectively." (PMID 35515348, 2022). "In conclusion, this case suggests that aGCC may trigger amphiphysin-IgG autoimmunity, and amphiphysin-IgG autoimmunity could relapse with a different clinical phenotype months after the initial episode, so long-term follow-up is needed." (PMID 36685551, 2022). "Four children with anti-amphiphysin autoimmunity were identified (1/4 female)." (PMID 35515348, 2022). "Tumor cells showed reactivity with amphiphysin-Abs, which indicates that the aGCC might play a role in triggering amphiphysin-IgG autoimmunity." (PMID 36685551, 2022). "This case suggests that aGCC may trigger amphiphysin-IgG autoimmunity." (PMID 36685551, 2022).